PRF1 (perforin 1)
Diseases named in the same sentence as PRF1 in open-access papers (continued):
Sharing a sentence is not in itself a finding about the gene and the disease.
tumor (continued). "Moreover, they express effector molecules, which are destined to kill tumor cells, including perforin 1, granzyme B and TNFα, as well as multiple pro-inflammatory cytokines that are characteristic for activated macrophages and Th1 cells, including IL-1β, IL-6, IL-2 and IFNγ." (PMID 37174085, 2023). "RIME was negatively correlated with NK cells, CD8+ T cells, and M1 macrophages, alongside various tumour‐suppressive cells, as well as tumour‐killing activity indicators, including PRF1, GZMA, and cytolytic activity, which suggests that RIME might be involved in tumour immune evasion." (PMID 37712124, 2023). "In addition, the expression level of PRF1 is related to tumour prognosis." (PMID 35473583, 2022). "The expression of T cell activation markers (CD25 and CD69), as well as anti-tumor cytokines (GZMB, IFNγ, and PRF1), was significantly suppressed when incubated with the supernatants of NAC-pre-treated neutrophils." (PMID 41516400, 2026). "Exosomes derived from these CAR-T cells carrying PRF1 and GZMB exhibited high cytotoxicity against TNBC cell lines and reduced tumor volumes in xenograft models, highlighting the potential of exosome-mediated therapy in TNBC." (PMID 40281554, 2025). "Our data demonstrate that PRF1 and GZMB expression levels are elevated in the peritumoral region compared to the tumor core, suggesting a spatial heterogeneity in cytotoxic immune activity." (PMID 40895524, 2025). "On day 4 and 14 (for Prf1-/-) or on day 4 and 17 (for Ifng-/-), GFP+ tumour cells were sorted and co-cultured with freshly prepared NK cells." (PMID 39642167, 2025). "Among these, GZMK+ CD8+ T cells, GZMB+ CD8+ T cells, and NK cells exhibited high levels of effector cytotoxic genes such as GZMA, GZMB, NKG7, PRF1, and GNLY, contributing significantly to anti-tumor immunity." (PMID 40149859, 2025). "To dissect the two main functions of NK cells, namely killing tumour cells and producing IFN-γ, we analysed the clonal evolution of B-ALL cells co-cultured with Prf1-/- and Ifng-/- NK cells, respectively." (PMID 39642167, 2025). "This study explored the role of perforin-1 (PRF1) and granzymes A, B and K (GZMA, GZMB and GZMK) in cancer biology, focusing on their impact on tumor cell death and immune response modulation." (PMID 40002821, 2025). "Flow cytometry analysis of tumor‐infiltrating CD8+ T cells revealed that cotreatment with V‐9302 and anti‐PD‐1 significantly enhanced the expression of cytolytic proteins (GZMB and PRF1) and effector cytokines (IFN‐γ and TNF‐α) compared to monotherapy groups." (PMID 40575936, 2025). "This signature includes key genes for maintaining cellular cytotoxicity such as ZNF683,41PRF1, IL2RB, and IFNG and immune activation and exhaustion markers including LAG3, PDCD1, PRF1, and TBX21 that contribute to anti-tumor immunity." (PMID 41045934, 2025). "These cells exhibit elevated expression of cytolytic effector molecules, such as PRF1 and GZMB, supporting their role in persistent tumor surveillance." (PMID 40859981, 2025). "CYT, an important indicator of the anti‐tumor immune activity of CD8+ cytotoxic T cells, is determined by the expression levels of PRF1 and GZMA." (PMID 41223031, 2025). "ELISA analysis demonstrated significantly increased secretion of Perforin-1 and Granzyme-B in KO-HMGB2 NK cells in response to tumor stimulation." (PMID 41280896, 2025). "Gene expression analysis revealed higher levels of activation, cytotoxicity, and memory markers (e.g., CD69, PRF1, TNF, KLRB1, and NCR3) in iMRAS-activated CAR-iNKT cells, correlating with their enhanced tumor-killing potential." (PMID 40297706, 2025). "CD8+ effector T cells (cytotoxic T lymphocytes, CTLs) serve as key mediators of antitumor immunity by recognizing tumor cells through MHC class I molecules and inducing apoptosis through the release of perforin‐1 (PRF1), granzyme B (GZMB), and IFN‐γ." (PMID 40859981, 2025).
tumor (continued). "The transcriptomic data showing upregulation of cytolytic genes (GZMs, PRF1) and survival regulators (FOS/JUN family) in the 15.CAR-T cells offers a mechanistic explanation for their superior anti-tumor activity." (PMID 41154636, 2025). "Perforin-1 (PRF1), a cytotoxic molecule known to enhance anti-tumor immune responses, showed a positive correlation with LAG3 expression in this study." (PMID 40411616, 2025). "ITGAE is associated with a group of genes that have a cytotoxic function in CD8 cytotoxic T cells (CTSW, GNLY, NKG7, PRF1, GZMB, KLRK1) up-regulated in the tumor, identifying resident CD8 T cells in the tumor to have a highly cytotoxic and activated phenotype." (PMID 39548591, 2024). "NK cells, an essential component of the innate immune system, exhibit the ability to directly eliminate tumor cells through the secretion of cytotoxic molecules such as GZMB and PRF1." (PMID 39439794, 2024). "In the granule exocytosis pathway, perforin 1 delivered Granzyme B (GZMB) into tumor cells and induced tumor cell death." (PMID 38360696, 2024). "NK cells can be activated by tumor cells, cytokines [e.g., interleukin (IL)-2, IL-12], natural products (e.g., chitosan) to induce direct lysis of tumor cells through the secretion of toxic molecules [e.g., granzyme B (GZMB) and perforin (PRF1)]." (PMID 39439794, 2024). "Our results showed that the expression of CXCL9, CXCL10, GZMA, GZMB, PRF1 and IFNG was significantly higher in tumor tissues than in adjacent normal tissues in GC patients." (PMID 39376571, 2024). "In patients with fHLH, mutations in genes that regulate granule-dependent cytotoxicity in CD56dim NK cells (including PRF1, UNC13D, RAB27a, and STX11) can result in defective clearance of infected or tumor cells." (PMID 38448692, 2024). "Consistent with the regulon profile, tumor-reactive T cells exhibited higher expression of pro-inflammatory effector molecules such as IFNG, TNF, and PRF1 and lower expression of genes like LBT, CD27, and CD28." (PMID 39243082, 2024). "In IGHV-unmutated cases, they reported methylation of known or potent tumor suppressor genes (for example, VHL, ABI3, and IGSF4) as well as unmethylated genes involved in cell growth and tumor progression (ADORA3 and PRF1)." (PMID 38435839, 2024). "The PRF1 cluster also upregulated Th1 markers IFNG and CXCL13, which contribute to tumor control by up-regulating HLA-II and promoting the formation of tertiary lymphoid structures (TLS), respectively." (PMID 37185301, 2023). "Accordingly, FGFBP2+NKT cells expressed the highest levels of cytotoxic genes, such as GZMB, GZMH, PRF1, and GNLY, indicating that FGFBP2+NKT cells had the strongest tumor-killing effects." (PMID 38065972, 2023). "PRF1, GZMA, and GZMK, 3 key effector molecules, were shown to be upregulated, and Rg1-pretreated T cells showed a stronger tumor lytic function at different effector: target cell ratios." (PMID 37546705, 2023). "Consistently, the tumor-infiltrating GZMAhigh NK subcluster expressing a high level of cytotoxic genes (GZMA, GZMB, GZMK, GZMM, GZMH, PRF1, and GNLY) and FASL and TRAIL genes was most enriched in the PD-1+SMI group." (PMID 37430270, 2023). "Both activated CD8+ T cells and NK cells show cytolytic activity against tumor cells by secreting several cytolytic molecules, such as granzyme A (GZMA), GZMB, and perforin (PRF1), showing good prognoses in various types of cancers." (PMID 38203530, 2023). "We also observed increased expression levels of immune‐related genes, such as SLAMF7, TNFSF8, BTN3A1, CD2, LGALS9, PRF1, and MX2, in tumor samples from the MT group of the Local‐SCLC cohort." (PMID 38125769, 2023). "Subclusters with Entpd1 expression were assigned as tumor-specific T cells, including Treg (CD4+Foxp3+), CD8+ effector (Gzmb+Prf1+Ifng+), CD8+ effector memory (Cd44+Cd69+), CD8+ exhausted subclusters (Pdcd1+Lag3+Tigit+Havcr2+)." (PMID 36209176, 2022).
tumor (continued). "CD103+ CD4+ T cells exhibit an immunosuppressive phenotype and high retention capacity in GC tumor tissues, leading to CD8 + T cell dysfunction, and granzyme B (GZMB), interferon-γ (IFN-γ), tumor necrosis factor α (TNF-α), and perforin (PRF-1) reduction." (PMID 36341377, 2022). "With correlating gene expression profiles of cytotoxic T lymphocyte (CTL) markers (CD8A, CD8B, GZMA, GZMB, and PRF1) with T-cell characteristics, the TIDE algorithm predicts immunotherapy of tumor patients." (PMID 36618968, 2022). "CD8-05-FGFBP2 cluster exhibited a CD8+ effector phenotype, upregulating genes involved in cytotoxicity and anti-tumor activity: FGFBP2, GNLY, FCGR3A, GZMH, PRF1, TGFBR3, and GZMB." (PMID 36350695, 2022). "Mechanistically, we found that the combination therapy increased the number of Prf1- and GzmB-expressing CD8+ T cells, increased tumoral GzmB expression, and decreased tumor cell proliferation." (PMID 35380995, 2022). "In the study, we found that, in comparison to wild-type animals, Tmem176b knockout lowered the expression of IFN-γ, PRF1 and GZMB in TIL CD8+ T cells, indicating that the function of tumor-infiltrating T cells was suppressed." (PMID 35399535, 2022). "For CD8+ T cells, although the cytotoxic molecules (GZMA, GZMB, NKG7, and PRF1) were highly expressed, a fraction of CD8+ T cells showed positive with exhaustion biomarkers (CTLA4, PDCD‐1, and TIGIT), indicating their tumor‐cytotoxic activity was constrained." (PMID 34185421, 2021). "In fact, our data on TILs shows prominent upregulation of perforin 1 (PRF1), granzymes K (GZMK) and M (GZMM), which are key for lymphocyte anti-tumor cytotoxicity." (PMID 34084172, 2021). "Of the five GSDM gene members, only GSDMD expression showed a positive correlation with CD8+ T cell marker genes (e.g., CD8A, CD8B, PRF1, GZMA, GZMB, and IFNG) in CTLs across all three tumor cohorts." (PMID 34429144, 2021). "In line, T cells with clonal expansion expressed GZMA/B, PRF1, INFG, and MIK67, indicating their tumor-reactive and cytotoxic state." (PMID 33686071, 2021). "We defined tumors with simultaneous upregulation of PRF1 and GZMB (CytAct Up, z-Score = 0) as tumors with increased anti-tumor immunity." (PMID 32523042, 2020). "Tumors with a simultaneous downregulation of PRF1 and GZMB (CytAct Down) were defined as tumors with downregulated anti-tumor immunity." (PMID 32523042, 2020). "Expression of membrane receptors such as FCGR3A and CX3CR1, and cytotoxic genes like GZMB, FGFBP2, PRF1, and GNLY increased gradually during this transition, implying a gradually acquired tumor-killing ability in CD56dim NK cells." (PMID 33298893, 2020). "Altogether, these data bring to light the importance of the PRF1/GZM pathway in cancer immunosurveillance, since tumor cells have developed a myriad of mechanisms to interfere with this process, acquiring resistance to NK cell-mediated apoptosis." (PMID 32466293, 2020). "Activation of T cells was observed and tumor killing activity was noticed in 6 PDOs by assessing interferon‐gamma (IFNG), granzyme B (GZMB), and perforin‐1 (PRF1) of CD3+TILs, data that is consistent with clinical trials for different cancer types." (PMID 33042756, 2020). "Based on the co-expression correlation between CD274 and CD8A in 29 tumor types, and between GZMA and PRF1 in 32 tumors, we further classified TME into eight groups according to IRGs’ expression level." (PMID 33585244, 2020). "ENTPD1 (expressed on tumor-specific T cells), as well as the cytotoxic factors granzyme B (GZMB) and perforin 1 (PRF1), expressed by T cells and NK cells, showed progressive decrease." (PMID 33276569, 2020). "Consistent with the cytotoxic activity, Ly6C+CD8+ population from EMT6 tumor-primed mice expressed higher levels of IFNG, GZMA, GZMB, and PRF1 as assessed by qPCR analyses." (PMID 30926774, 2019).
tumor (continued). "The release of cytotoxic granules containing perforin (PRF1) and GZMB by NK cells is one of the major mechanisms responsible for tumor cell killing by NK cells." (PMID 31540045, 2019). "The expression of genes related with tumor microenvironment (CD8A, GZMA, and PRF1) can also affect anti-CTLA-4 and anti-PD-1/PD-L1 therapy." (PMID 32793247, 2018). "A set of tumor cytotoxic genes were up-regulated in CIK cells, including GZMB, FASL, PRF1, TNFα, CD40L, and IFN-γ." (PMID 30333226, 2018). "We detected a statistically significant increase in mRNA levels of IFN-γ, granzyme B, TNF-α and perforin 1 in CD8+ TIL from Grail−/− mice, further supporting that Grail controls the effector function of CTLs infiltrated into the tumours." (PMID 28798332, 2017). "The Perforin-1 knockout mice also fail to clear LCMV in vivo, and they eliminate tumor cells with reduced efficiency." (PMID 27857713, 2016). "It is possible that methods overcoming cancer-induced neutralization of Perforin-1 through suppression of CD8+ CTL induction or activity, in combination with tumor-specific cancer vaccines that generate CD8+ CTL, will allow remission or even cure of cancer." (PMID 27857713, 2016). "Except for OSM, the expression of all anti-tumor genes including TNF-α, PRF1, GZMB, FasL, TNFSF10 and CD40LG were significantly upregulated in CIK cells compared to PBMC, which were negatively correlated with expression profiles of their potential regulators." (PMID 25826780, 2015). "Perforin-1, IFN-γ, STAT-1 and T cells each contribute to reducing 3-MCA-induced tumor formation and growth." (PMID 26555296, 2015). "In contrast, miR-27a* is able to negatively regulate NK cell cytotoxicity by silencing the genes PRF1 and GZMB, as shown by the knockdown of miR-27a* in NK cells, which leads to decreased tumour growth in a human tumour xenograft model." (PMID 23478435, 2013). "Specifically, granzyme A (GZMA), granzyme B (GZMB), granzyme K (GZMK) and perforin-1 (PRF1) do not only induce apoptosis and modulate immune response within the tumor microenvironment (TME), but also have other diverse roles, such as potentially regulating homeostasis post-infection." (PMID 40002821, 2025). "However, it did enhance anti-tumor T-cell responses, increasing the presence of PD-1+ CD62Llow CD4+ and CD8+ T-cells and the production of PRF1, TNF-α, and IFN-γ." (PMID 40281554, 2025). "PD-1 and LAG-3 double knockout CD8+ T cells exhibit higher TCR diversity, stronger cytotoxicity (increased expression of GZMB and PRF1), and IFN-γ dependent anti-tumor effects, while the combination of PD-1 with TIM-3 or TIGIT blockade is still in the exploratory stage." (PMID 40821806, 2025). "In contrast, the presence of Prf1-/- NK cells led to a drastically lower number of primary and secondary resistant tumour cell clones (primary resistant: B-ALL+Prf1-/- NK cells n=96 vs B-ALL+WT NK cells n=245; secondary resistant: B-ALL+Prf1-/- NK cells n=15 vs B-ALL+WT NK cells n=56)." (PMID 39642167, 2025). "Since T cell depletion did not alter the anti-tumor effects of mDKN01, findings in Prf1−/− mice suggest that DKK1 supports tumor progression through suppression of NK cell function." (PMID 39885132, 2025). "Cells in cluster 5 expressed homing receptor genes (Sell and Ccr7) but exhibited little to no expression of effector molecule genes (Gzmb, Ifng, and Prf1), suggesting that they do not directly participate in anti-tumor responses." (PMID 39925817, 2025). "Tumour‐infiltrating CD8+ T cells can be found in different states, including effector cytotoxic CD8+ T cells that express granzyme B (Gzmb) and perforin (Prf1), and stem‐like TCF1+ CD8+ T cells that lack effector functions but can replenish the cytotoxic CD8+ T cell pool." (PMID 40745918, 2025). "Indeed, within tumor‐infiltrating NK cells, NKG7—while highly expressed and a strong correlate of cytotoxicity signature—was surpassed by GZMA and PRF1 in terms of correlation with cytotoxicity score." (PMID 40538191, 2025).
tumor (continued). "One subpopulation expressed CD44 + CXCR3 + CXCR4 + PRF1 + and GZM family genes, while the other expressed XCL1 + NCAM1 + GNLY + and KIR family genes, suggesting that these T cells possess a robust capacity to mediate tumor cell apoptosis." (PMID 40411616, 2025). "In mouse tumor model, the frequency of MDSCs inversely correlates with the expression of NK cell-activating receptors including NKG2D and natural cytotoxicity triggering receptor 3 on the NK cell surface, as well as with IFNγ and PRF1 (perforin 1) production." (PMID 39229258, 2024). "T127 tumor cells treated in vitro with AZD5305 and then cocultured in a transwell system with C5aR1 macrophages resulted in C5aR1 macrophages that suppressed T cell activation as assessed by positivity for GMZB, PRF1 or IFNγ." (PMID 38802355, 2024). "Conversely, immune activity-related signatures, including PRF1, GNLY, GZMA, GZMB, and interferon regulatory factor 1, play crucial roles in tumor cell recognition and tumoricidal, with connections to extended survival, and identifying responders to anti-PD-1 antibody treatment." (PMID 38956740, 2024). "In addition, we observed an increase in the expression of cytotoxicity (PRF1, GNLY, GZMB) and proliferation (MKI67) markers in the CD8+ T cells in PI3K/mTORi+PD‐1i‐treated tumours." (PMID 38711203, 2024). "In addition, Ce6-mediated PDT effectively inhibited hPD-L1 MC38 tumor growth by enhancing tumor-infiltrating CD8+ T cells and Gzmb and Prf1 release in the TME and augmenting the antitumor immune response in mice bearing hPD-1/PD-L1 MC38 tumors." (PMID 37762216, 2023). "And for the clinical relevance of IL2RA expression patterns, there was of significant difference in clinical grade, indicating that PRF1 and IL2RA might be involved in the mechanism of tumor progress." (PMID 36097539, 2022). "Of note, the expressions of GZMB and PRF1, which are essential effector molecules for NK cell cytotoxicity, are found significantly lower in tumor tissues compared with adjacent nontumor tissues of JORRP patients." (PMID 35350785, 2022). "In the comparison of differentially expressed genes (DEGs) between LUAD and normal tissues, three genes (FGFBP2, CRIP1, and PRF1) were mainly expressed in normal tissues but not in tumor-derived cells." (PMID 36483553, 2022). "C5,6,7_CD8, which was predominantly composed of CD8+ T cells from tumor tissue and blood, exhibited high gene accessibility of cytotoxic molecules including GNLY, PRF1 and GZMB, with cells in C6_CD8 exhibiting the highest accessibility for these cytolytic molecules." (PMID 35668194, 2022). "In addition, the tumor-restricted clonotypes expressed lower effector markers (GZMB, PRF1, IFNG) compared with clonotypes shared with other tissues, indicating possible antigen-experience and exhaustion of TCR clonotypes in the TME." (PMID 36185254, 2022). "Both subsets of CD8+ T cells from tumor samples expressed higher effector genes than nonmalignant samples, including chemokines (e.g., CCL5), cytotoxicity-associated genes (PRF1, GZMA, GZMB, GZMH), and proinflammatory cytokines (e.g., IL-32)." (PMID 34921160, 2021). "We also measured perforin (PRF1) and granzyme A (GZMA) gene expression as representations of cytolytic activity (CYT) in tumors and found that CYT was inversely correlated with tumor stages across all cancer types (n = 6,458, 25 tumor types)." (PMID 34698427, 2021). "The PDO TILs activities were evaluated by treatment with anti-PD-1 or anti-PD-L1 in murine tumor organoids that showed a strong increase of CD8 TILs and T cell activation markers such as interferon-gamma (IFNγ), perforin-1 (PRF1), and granzyme B recapitulating the PD-1/PD-L1 immune checkpoint." (PMID 34074330, 2021). "II of CD8 T cells producing both GZMB and perforin (PRF1) was greater in the patients with lower rather than higher tumour grade (P = 0.017)." (PMID 32277125, 2020).